CALML3 (calmodulin like 3)
Diseases named in the same sentence as CALML3 in open-access papers:
CALML3 is named in the same sentence as 36 diseases in open-access papers, as found by Europe PMC text mining. Sharing a sentence is not in itself a finding about the gene and the disease. The quoted sentences say what the papers report.
breast carcinoma (6 papers, 2013 to 2023). "Previously, loss of CALML3 immunoreactivity has been linked to early breast cancer development." (PMID 23935623, 2013). "Knocking down ZNF423 or CALML3 altered the breast cancer cell response to several drugs including 4-OH-TAM, raloxifene, olaparib (PARP inhibitor) and cisplatin (platinum)." (PMID 28821270, 2017). "CALML3 is a calcium-sensing protein known to be highly expressed in epithelial cells, including tissues such as breast, and it is downregulated in breast cancers and transformed cells in culture." (PMID 28821270, 2017). "We knocked down CALML3 and ERα individually in these breast cancer cells that had been treated with E2 alone or E2 in combination with SERMs, followed by determining mRNA and protein levels." (PMID 28821270, 2017). "CALML3 expression is downregulated in breast cancers and transformed cell lines making it an attractive marker for tumor formation." (PMID 23638045, 2013). "CALML3 is downregulated in breast cancer and transformed cells in culture." (PMID 28821270, 2017). "CALM2 and CALML5 were found to be significantly active in primary breast cancer, whereas CALML3 and CALML6 were significantly active in liver metastasis of breast cancer." (PMID 37958607, 2023). "We found that CALM2 and CALML5 were significantly active in primary breast cancer, while CALML3 and CALML6 were significantly active in breast cancer liver metastasis." (PMID 31557971, 2019). "The mRNA expression of those canonical ER-targeted genes including EFP, COX7RP and EBAG9 were induced after E2 treatment as expected in breast cancer cells, but did not change significantly after knockdown of CALML3 compared to the control." (PMID 28821270, 2017). "Based on the observations we made in LCLs, we asked whether CALML3 might function as an ERα regulator, cooperating with ERα to regulate ZNF423 expression in ERα + breast cancer cells." (PMID 28821270, 2017). "Earlier studies indicated that CALML3 is downregulated in breast cancer and absent in most transformed cell lines." (PMID 23638045, 2013).
liver cancer (5 papers, 2018 to 2025). An epithelial or non-epithelial malignant neoplasm that arises from the liver. "Another calmodulin-like protein, CALML3, is a tumor suppressor gene, which significantly inhibits liver cancer growth and lung metastasis." (PMID 33823876, 2021). "Our further experiments and clinical samples show that DNB with CALML3 reduced pulmonary metastasis in liver cancer." (PMID 29445139, 2018). "CALML3 was recognized as a crucial marker and suppressor for liver cancer metastasis." (PMID 38672263, 2024). "CALML3 is a gene with “early warning” value for liver cancer and lung metastasis, and it is expected to become a new marker for early diagnosis of lung metastasis of liver cancer and a new target for inhibiting liver cancer growth and lung metastasis." (PMID 33823876, 2021). "Moreover, CALML3, a biomarker of BC_P05T, may function as a tumour suppressor gene, offering an early warning value for pulmonary metastasis of liver cancer." (PMID 39877290, 2025). "Furthermore, by examining these signaling networks, we discovered that FOS (Fos proto-oncogene, AP-1 transcription factor subunit), LAMC2 (laminin subunit gamma 2), and CALML3 (calmodulin like 3) were the most significant gene nodes with high degrees involved in liver cancer." (PMID 32280695, 2020). "There were significant differences between patients with or without pulmonary metastasis, i.e., CALML3 expression in tumour tissue, tumour encapsulation, vascular invasion, Barcelona Clinic Liver Cancer (BCLC) stage and prothrombin time." (PMID 29445139, 2018).
gastric cancer (3 papers, 2016 to 2025). A primary or metastatic malignant neoplasm involving the stomach. "Despite the few data regarding CALML3, it was reported that metformin suppresses gastric cancer through stimulating CALML3 secretion from gastric tumor--associated fibroblasts, representing a novel anti-cancer mechanism of metformin, and a tumor-suppressive role of CALML3." (PMID 41465209, 2025). "We also found that CALML3 down-regulated significantly in gastric cancer patients." (PMID 26911362, 2016).
hepatocellular carcinoma (2 papers, 2018 to 2020). A malignant tumor that arises from hepatocytes. "To validate our miRNA-mRNA-pathway interaction network analysis, we examined the expression of FOS, LAMC2, CALML3, and their interacting miRNAs using 20 pairs of hepatocellular carcinoma samples and adjacent normal tissues by RT-PCR." (PMID 32280695, 2020). "To further explore the role of CALML3 in HCC metastasis, we performed gain-of-function and loss-of-function studies to detect the effect of CALML3 on oncogenic behaviours of hepatoma cells including cell growth, migration and invasion." (PMID 29445139, 2018). "The expression level of CALML3 in hepatoma cell lines with high metastatic potential was remarkably lower than in those with lower metastatic potential, confirming that CALML3 was a metastasis suppressor." (PMID 29445139, 2018).
Obesity (2 papers, 2019 to 2023). Accumulation of substantial excess body fat. "Higher OR4D1 gene score smokers were at a greater risk of obesity (OR = 2.67 [CI = 1.35, 5.30]), while high CALML3 gene score smokers had a lower risk of obesity (OR= 0.25 [CI = 0.10, 0.62])." (PMID 37664850, 2023). "OR4D1, and OR52K1 gene scores were positively correlated with obesity, and OR2L8 and CALML3 gene scores were negatively correlated with obesity." (PMID 37664850, 2023). "Until now, the specific roles of ANO2, CAMK2D, SLC8A1, PDE2A, CALML3, GNG7, and CALML6 genes in olfactory-related dietary patterns and obesity in humans have not been apparently explored; therefore, further investigation in these research areas is warranted." (PMID 31057674, 2019).
oral cancer (2 papers, 2013 to 2018). "Because the specific expression and cellular localization of CALML3 indicate normal cell function, the potential for development of a simple diagnostic test for oral cancer using CALML3 as a marker is promising." (PMID 23935623, 2013). "There were other reports that CALML3 was highly expressed in normal differentiation of epithelial tissues, such as breast, thyroid, prostate, kidney and skin, and also significantly downregulated in breast tumours, oral cancers and skin cancers." (PMID 29445139, 2018). "A change in CALML3 expression could indicate the presence or the early developing stage of oral cancer." (PMID 23935623, 2013). "CALML3 may thus be a sensitive new marker for oral cancer screening." (PMID 23935623, 2013).
actinic keratosis (1 paper, 2013). A precancerous lesion of the skin composed of atypical keratinocytes. "Here we focus on CALML3 expression in actinic keratosis (AK), squamous cell carcinoma (SCC), and basal cell carcinoma (BCC)." (PMID 23638045, 2013). "The objective of this study was to survey CALML3 localization in normal epidermis and in hyperproliferative skin diseases including actinic keratosis, squamous and basal cell carcinoma as well as verruca and psoriasis and to compare CALML3 immunoreactivity with the proliferation marker Ki-67." (PMID 23638045, 2013).
carcinoma in situ (1 paper, 2013). "In addition, direct comparisons in CALML3 expression were made between the individual categories of benign, dysplasia, carcinoma in situ, and invasive squamous cell carcinoma." (PMID 23935623, 2013).
dysplasia (1 paper, 2013). A usually neoplastic transformation of the cell, associated with altered architectural tissue patterns. "Benign tissue specimens had significantly more CALML3 expression in the superficial mucosa compared to invasive specimens (P < 0.001) and dysplasia/CIS specimens (P = 0.013), as revealed by a comparison of the total stain scores." (PMID 23935623, 2013). "A strong reduction (or complete lack) of CALML3 immunostaining was seen in invasive squamous cell carcinoma compared to both benign tissue and dysplasia/CIS tissue, although in low-grade invasive squamous cell carcinoma, keratin pearls did illustrate mild immunoreactivity." (PMID 23935623, 2013).
endometrial cancer (1 paper, 2023). Primary or metastatic malignant neoplasm involving the endometrium (mucous membrane that lines the endometrial cavity). "A four-marker panel comprising of SPRR1B, CRNN, CALML3 and TXN predicted endometrial cancer with an AUC of 0.80 (0.71–0.88)." (PMID 36807337, 2023). "Urine SPRR1B, S100A7, CALML3 and TXN were also found to have potential as endometrial cancer biomarkers." (PMID 36807337, 2023). "CRNN, CALML3 and TXN predicted endometrial cancer with AUC values of 0.75 (0.64–0.84), 0.75 (0.65–0.84) and 0.75 (0.66–0.85) respectively." (PMID 36807337, 2023).
glioma (1 paper, 2021). A benign or malignant brain and spinal cord tumor that arises from glial cells (astrocytes, oligodendrocytes, ependymal cells). "The expressions of CALML5, CALM3 and CALML3 were upregulated in IDH mutant glioma." (PMID 34070840, 2021).
Huntington disease (1 paper, 2020). Huntington disease (HD) is a rare neurodegenerative disorder of the central nervous system characterized by unwanted choreatic movements, behavioral and psychiatric disturbances and dementia. "CALML3 interacted with hsa-miR-765 and played a regulatory role in GnRH signaling pathway, long-term potentiation, and Huntington's disease." (PMID 32280695, 2020).
ichthyosis (1 paper, 2013). Disorders of cornification that are characterized by visible scaling and/or hyperkeratosis of most or all of the skin. "CALML3 staining was also investigated in specimens of verruca (warts) and ichthyosis, two additional types of skin lesion characterized by a thickening of the epidermis and keratinocyte hyperproliferation." (PMID 23638045, 2013). "In contrast, CALML3 may be aberrantly expressed and/or downregulated in hyperproliferative disorders such as psoriasis and ichthyosis, as well as in pre-cancerous lesions (such as AK) and in squamous cell and basal cell non-melanoma skin cancers." (PMID 23638045, 2013). "CALML3 staining was also investigated in tissue sections of non-cancerous hyperproliferative skin lesions including verruca, ichthyosis and psoriasis." (PMID 23638045, 2013).
invasive carcinoma (1 paper, 2013). A carcinoma that is not confined to the epithelium, and has spread to the surrounding stroma. "CALML3 was strongly expressed in benign oral mucosal cells with downregulation of expression as squamous cells progress to invasive carcinoma." (PMID 23935623, 2013).
psoriasis (1 paper, 2013). An autoimmune condition characterized by red, well-delineated plaques with silvery scales that are usually on the extensor surfaces and scalp. "Localization of CALML3 in acanthoma, verruca (warts) and the inflammatory hyperproliferative skin disease psoriasis is also examined and discussed." (PMID 23638045, 2013).
cancer (12 papers, 2013 to 2025). A tumor composed of atypical neoplastic, often pleomorphic cells that invade other tissues. "Missense mutations were noticed in all genes except CALML3 and IL1B.On the other hand methylation of hub genes were depicted in in which CCR9 and MUC5B were hypermethylated in CESC which can lead to gene silencing and promote metastasis of cancer." (PMID 40653567, 2025). "The roles of LINC01322 and CALML3 in cancers were also revealed by previous studies." (PMID 35433477, 2022). "Next, in examining the relationship between the initiation of metastasis and biological functions enriched by CALML3 and its 53 inversing DEGs before and after the critical period of metastasis initiation, we found that most typical cancer-related pathways (e.g., apoptosis, HIF-1) were enriched." (PMID 29445139, 2018). "And most of the 24 DEPs (CDK1, SFN, PRKAR2B, MKI67 and MDK involved in the cell cycle; LOXL2, P4HA1, P4HA2, SPRX, DES, PRPH and CALML3 involved in construction and regulation of extracellular matrix; IL33 and EHD3 may involve in immune) were linked to cancer hallmarks." (PMID 33200655, 2020). "Because loss of CALML3 expression appears to occur very early in cancer development, CALML3 immunostaining may not be particularly useful in staging the progression of existing cancer." (PMID 23638045, 2013). "Interestingly, Metascape for the first time demonstrated a physical interconnection between CALML3 and DNA repair proteins (BRCA2—Breast Cancer Gene 2, BLM—Bloom syndrome protein, SLX4—Structure-Specific Endonuclease Subunit)." (PMID 41465209, 2025). "On the other hand, as in the cancer specimens, CALML3 expression was always absent in areas of high proliferation." (PMID 23638045, 2013).
tumor (11 papers, 2013 to 2025). "In all samples analyzed, there was an inverse relationship between Ki-67 and CALML3 staining, where CALML3 was consistently reduced with loss of nuclear localization in tumor regions with abundant Ki-67 staining." (PMID 23638045, 2013). "When residual CALML3 expression was detected in the tumor, it was mostly cytoplasmic and there was a consistent loss of CALML3 labeling in the nucleus." (PMID 23638045, 2013). "The underlying Ki-67-positive tumor shows reduced CALML3 immunoreactivity and loss of CALML3 nuclear staining." (PMID 23638045, 2013). "CALML3 was found to be downregulated during tumor progression which would explain its increased level during WWOX overexpression but decreased level during AP-2γ overexpression." (PMID 35563688, 2022). "This suggested that the tumour suppressor CALML3 played a critical role in metastasis initiation, directly or proximally regulating these reversing DEGs at a molecular network level." (PMID 29445139, 2018). "Clinicopathologic analysis showed that CALML3 expression was significantly correlated with tumour encapsulation, vascular invasion, tumour size and BCLC stage." (PMID 29445139, 2018). "CALML3 expression was remarkably reduced in the tumour tissues (average score, 3.84 ± 3.14), comparing with the corresponding peritumoural liver tissues (average score, 7 ± 3.22) (P < 0.001)." (PMID 29445139, 2018). "With a multivariate Cox regression model, intratumoural CALML3 expression, tumour encapsulation, vascular invasion, BCLC stage and TB were factors related to OS." (PMID 29445139, 2018). "Inducible CALML3 expression group exhibited less weight and volume of tumours, as well as less pulmonary metastasis nodules and incidence than the control." (PMID 29445139, 2018). "Intratumoural CALML3 expression, tumour encapsulation, vascular invasion, tumour size, Edmondson grade, BCLC stage and prothrombin time were significantly associated with the RFS." (PMID 29445139, 2018). "In this study, to better elucidate the role of CALML3 as a tumour suppressor in HCC metastasis, we performed endogenous genetic tests on gain-of-function and loss-of-function, respectively." (PMID 29445139, 2018). "But as a suppressor gene and an indicator of HCC development, CALML3 expression was significantly reduced in HCC tumour tissues and thus was relatively harder to be detected than oncogenes with high expression." (PMID 29445139, 2018). "We also created xenografts models of the control HCCLM3 and CALML3 overexpression HCCLM3 cells with fluorescent proteins as above; CALML3 overexpression significantly inhibited tumour growth and tumour pulmonary metastasis." (PMID 29445139, 2018). "Thus, based on IHC analyses in tumour tissue slices from patients, we showed that CALML3 was a predictor of HCC metastasis, to guide the clinical diagnosis and early treatment of HCC patients." (PMID 29445139, 2018). "Furthermore, the expression level of CALML3 may indicate the degree of tumour malignancy for HCC, and especially pulmonary metastasis initiation." (PMID 29445139, 2018). "In addition, to further verify the role of CALML3 as a tumour suppressor, we overexpressed CALML3 in HCCLM3 cells with high metastatic potential and decreased CALML3 expression in HepG2 cells with low metastatic potential by lentiviral-mediated expression and RNA interference, respectively." (PMID 29445139, 2018). "The MCC marker CCER2 was strongly expressed in the tumor, while epidermal MCC-associated genes, such as S100A2 and CALML3/5, were largely absent in MCC cells, but highly expressed in the epidermis." (PMID 41131107, 2025). "In total, sixteen clinical characteristics (e.g., tumour encapsulation, vascular invasion, tumour number, tumour size, BCLC stage, intratumoural CALML3 expression and so on) were analysed to identify factors associated with overall survival (OS) and relapse-free survival (RFS)." (PMID 29445139, 2018).
tumor (continued). "The expression of CCR9 and CALML3 mRNA was shown to be considerably reduced in tumor tissues when compared to non-tumor tissues as shown in To explore the prognostic importance of the hub genes we received overall survival plots (OS) using Kaplan–Meier method for each candidate hub genes." (PMID 40653567, 2025).
skin disorder (1 paper, 2013). Any deviation from the normal structure or function of the skin or subcutaneous tissue that is manifested by a characteristic set of symptoms and signs. "Paraffin-embedded tissue sections from normal human skin and hyperproliferative skin disorders were examined by immunohistochemistry and analyzed for localization and expression of CALML3 and Ki-67." (PMID 23638045, 2013). "Analysis of CALML3 expression status, and particularly its localization at the periphery and in the nucleus of differentiated cells in the epidermis may become a useful tool in the differential diagnosis of non-malignant versus malignant and invasive skin disorders." (PMID 23638045, 2013).
CALML3 also shares sentences with these, for which no sentence is quoted: breast tumours (1 paper); cervical cancer (1); cervix (1); Cognitive impairment (1); colorectal adenocarcinoma (1); colorectal cancer (1); gastric tumor (1); invasive ductal carcinoma (1); ischemic stroke (1); lobular carcinoma (1); melanoma (1); metastasis (1); neurodegenerative disease (1); non-melanoma skin carcinoma (1); prostate carcinoma (1); skin cancer (1); squamous cell carcinoma (1); Stroke (1).